FOXM1 (forkhead box M1)
Diseases named in the same sentence as FOXM1 in open-access papers (continued):
Sharing a sentence is not in itself a finding about the gene and the disease.
cancer (continued). "Moreover, the conjugation of the FOXM1-specific DNA aptamer (which inhibits FOXM1 transcriptional activity) to the polymersome surface enhanced the cytotoxic effect, thereby promoting the apoptosis of cancer cells." (PMID 41427517, 2026). "While the upregulation of FOXM1 in cancer contexts has been shown before, we present here that this gene is consistently upregulated in a pan-cancer manner, constituting a recurring mechanism cancer adopts to increase cell proliferation, one of the hallmarks of cancer." (PMID 39858603, 2025). "Consequently, targeting the transcriptional activity of FOXM1 or disrupting its interaction with other cancer-related pathways or transcription factors could represent a promising strategy for the development of novel anti-tumor therapeutics." (PMID 39781349, 2025). "However, we do show in our analysis that FOXM1 is likely one of the cancer master regulators, which may further corroborate the notion of FOXM1 as the ideal and central carrier of pro-proliferative signals." (PMID 39858603, 2025). "However, three limitations to hypothetical anti-FOXM1 pan-cancer therapy remain." (PMID 39858603, 2025). "However, FOXM1 expression is significantly upregulated in a wide range of cancers, including OC." (PMID 40746724, 2025). "High FOXM1 levels are generally associated with therapeutic resistance of cancer cells and poor prognosis of cancer patients due to decreased efficacy of the traditionally used therapeutic strategies, it shows that FOXM1 may serve as a selective target in human solid cancers." (PMID 38697979, 2024). "Notably, FOXM1 has demonstrated overexpression across a wide spectrum of cancers." (PMID 39272919, 2024). "Thus, FOXM1 might facilitate tolerance of high aneuploid tumors and provide advantages for aneuploid cancer development." (PMID 37452072, 2023). "Thus, FOXM1 and ERα share a mutual cancer-promoting regulatory relationship." (PMID 37370117, 2023). "In summary, our results provide a further understanding of HMGA1 in cooperation with FOXM1 within the nucleus to regulate gene transcription in controlling G2/M cell cycle progression, which could provide a potential cancer treatment strategy by targeting both HMGA1 and FOXM1 in cancers." (PMID 37240870, 2023). "Notably, in cancer tissues, prominent colocalization between FOXM1 and RNF112 was observed." (PMID 37288663, 2023). "Some have even suggested that FOXM1 might be the ‘’Achilles heel’’ of cancer." (PMID 37894854, 2023). "Therefore, there is a proposition that targeting FOXM1 could present a promising approach for cancer treatment." (PMID 37894854, 2023). "Therefore, inhibitory strategies for invasive FoxM1 based on its degradation, dephosphorylation, or inhibition of its transcription activity can be useful to suppress cancer metastasis and immune checkpoint evasion of cancer cells." (PMID 37968723, 2023). "Thus, we obtained the cell-penetrating DRI peptide M1-21 that could inhibit cancer cells probably by binding to FOXM1." (PMID 37344857, 2023). "In addition, FOXM1 can predict poor prognosis in some cancers." (PMID 36435510, 2022). "Thus SIRT2-activating molecules may be used to downregulate FOXM1 to diminish the proliferative potential of cancer cells." (PMID 35326523, 2022). "On the other hand, being the potent oncogene FoxM1, another member of the Forkhead family, negatively regulated by FoxO3a, its increased expression in more invasive and endocrine-resistant tumors, perfectly fits with the evidence of a defective FoxO3a in this subset of cancers." (PMID 35008379, 2022).
cancer (continued). "Collectively, these results implicate MYC, FOX (specifically FOXM1), and BRD family of TFs in the regulation of EP events through upregulation of CSFs and may represent master regulators of broad splicing changes associated with development and cancer." (PMID 36509773, 2022). "In addition, we tested whether the synthesized FOXM1-PROTAC had an effect on the tumorigenicity of cancer cells." (PMID 36171633, 2022). "In addition, FOXM1’s potential role in tumor immunology was investigated in different cancers." (PMID 36435510, 2022). "The cancer hallmark gene, FOXM1 was upregulated in almost all EOBRCA and not in LOBRCA." (PMID 36352274, 2022). "Because FOXM1 maintains cancer stem cells by inducing the epithelial–mesenchymal transition, a reduction in these mature hepatocyte metabolism-related genes might be accompanied by the loss of mature hepatocyte cell features due to the epithelial–mesenchymal transition." (PMID 35955438, 2022). "Hence, targeting the downstream target genes of FOXM1 may provide a promising molecular therapy for various malignant tumours." (PMID 35656815, 2022). "This work suggests that FOXM1-PROTAC may become a promising cancer treatment drug." (PMID 36171633, 2022). "Forkhead box M1 (FoxM1) could affect the progression of various carcinomas." (PMID 36301031, 2022). "Consistent with the observation that FoxM1 silencing is connected to reduced tumorigenicity, we found Artemisinin to considerably mitigate growth and clonogenicity of Hep3BshFoxM1 cells, implying the potential of this natural product in delaying or preventing tumor relapse in cancer patients." (PMID 34900697, 2021). "Considering an important influence of immune cells in cancer development and treatment, tissue cultures display a vital immunological compartment, and thus might help to understand the complex FOXM1 network in context of the TME and the effects of thiostrepton by modulating immune activation." (PMID 33668819, 2021). "Moreover, FOXM1 and cancer stem cell inhibitor monensin is under preclinical investigation." (PMID 33572108, 2021). "Based on recent studies of other cancer amplifications, we hypothesized that additional genes at 12p13.33 might harbor oncogenic functions that act in concert with FOXM1." (PMID 33890574, 2021). "However, FOXM1 overexpression in cancer promotes several aspects of cancer progression." (PMID 34206484, 2021). "Moreover, FoxM1 also can cross-talk with other signal pathways and promote progression of cancers." (PMID 33526768, 2021). "Regarding these aspects, several studies have reported the positive correlation between FOXM1 expression and cancer cell migration and invasion, as well as inhibiting FOXM1 via different methods, which resulted in a reduction in these activities of cancer cells." (PMID 34206484, 2021). "Therefore, FOXM1 may be a molecular target which present a synergistic clinical effect for cancers which express it as well as DKK1 and CKAP4." (PMID 34117362, 2021). "Hence, there is much interest in blocking FOXM1 activity in cancer." (PMID 34944900, 2021). "Hence, there should be therapeutic benefit from inhibiting the activity of FOXM1 in these cancers." (PMID 34944900, 2021). "Therefore, activating SIRT1 to deacetylate FOXM1 may become an efficient strategy for treating cancers with overexpressed FOXM1." (PMID 34769241, 2021). "Therefore, inhibition of FOXM1 may prove critical for developing effective therapeutic solutions for cancer chemoresistance problem." (PMID 34262016, 2021). "Furthermore, excluding kinase inhibitors and compounds not available for purchase, we compared the profiles of these hits with the changes in expression of established FOXM1 targets present in our dataset across seven cancer cell lines (A549, MCF7, VCAP, HA1E, A375, HCC515, and HT29)." (PMID 34262016, 2021). "Thus, HDACi combination with other anticancer agents could be a potential treatment option for cancer cells expressing FOXM1." (PMID 34335925, 2021).
cancer (continued). "Notably, FOXM1 was recently reported to induce DNA replication stress in vitro and FOXM1 expression was observed to correlate with expression of RS biomarkers in several cancer types, including HGSC." (PMID 34205406, 2021). "Therefore, FAM188B could be a critical therapeutic target to control cancers where FAM188B or FOXM1 are overexpressed." (PMID 33142744, 2020). "This activity is consistent with transgenic mice models showing that FOXM1 expression promotes early steps in tumorigenesis, promoting Clara cell and hepatocyte hyperplasia for example and acting in conjunction with many other carcinogens as well as cancer cell lines." (PMID 33253193, 2020). "Therefore, effective inhibition of FoxM1 could contribute to reduced tumorigenesis and cancer progression." (PMID 32429421, 2020). "Targeting FoxM1 may have promising therapeutic benefits for cancer treatment." (PMID 31992359, 2020). "Moreover, upregulated FOXM1 is related to poor prognosis in several cancers." (PMID 33053721, 2020). "We identified 28 gene sets and 95 core genes exacerbated in the C2 class, and two transcription factors (E2F1 and FOXM1) that are known to affect prognosis and response to therapy in different cancer types, and might be responsible for most of the differences between the two classes." (PMID 33396205, 2020). "Therefore, we examined the subgroup of LUAD samples, which had high expression of the three transcriptional regulators as well as many enhancer links (over 290 cancer-specific CENPA, FOXM1, or MYBL2 enhancer links), called “highly linked” samples for correlations to overall patient survival." (PMID 32925947, 2020). "Hence, targeting FOXM1 could be effective for treating several cancers and sensitizing drug-resistant cancer cells." (PMID 33053721, 2020). "In addition, FoxM1 overexpression has been linked with cancer progression and poor prognosis in several human cancers, suggesting that FoxM1 might play a crucial role in tumor initiation." (PMID 33214609, 2020). "Therefore, most cancer cells produce high level of FoxM1 to maintain their rapid growth." (PMID 32551039, 2020). "In addition, the concordant pattern of the FOXM1 expression emphasizes that the deregulated (most likely accelerated) cell cycle of those cancer cells partially mediated by FOXM1 is one of the key factors that must be considered when developing drugs for such cancers." (PMID 32858881, 2020). "Therefore, targeting FOXM1 could prove to be a useful new therapeutic strategy, allowing the suppression of multiple key cancer regulatory pathways." (PMID 32961773, 2020). "Indeed, targeting FOXM1 has been shown to significantly inhibit cancer growth and metastasis." (PMID 32372224, 2020). "In addition, FOXD2 and FOXM1 belong to the forkhead box (FOX) proteins, and FOX deregulation is known to be associated with many diseases, particularly for FOXM1, which is an oncogene that is overexpressed in most types of human cancer." (PMID 31561539, 2019). "Hence, compounds that inhibit FOXM1 activities might prove to be broadly useful in a variety of cancer types." (PMID 31815181, 2019). "In addition, the pan-cancer network contains the TFs FOXM1 and MYBL2 which support our finding." (PMID 31681566, 2019). "Importantly, FOXM1 mRNA and protein expression were highly correlated in pan-cancer, suggesting an important role for gene expression regulation in determining FOXM1 protein expression and its functional status in cancer." (PMID 30795624, 2019). "A recent study showed that TKIs could enrich cancer stem cells and induce epithelial–mesenchymal transitions, subsequently resulting in drug resistance, and these properties are associated with aberrant activation of the AKT/FOXM1/STMN1 axis." (PMID 30782607, 2019). "Interestingly, FOXM1 overexpression in hypoxia has been already documented in cancer." (PMID 30808328, 2019).
cancer (continued). "Our clinico-pathological data showed that FoxM1 over-expression was significantly associated with VEGF and MMP-9 expression, proteins implicated in tumor angiogenesis and extracellular matrix degradation respectively, thereby allowing cancer cells to invade and migrate to surrounding tissue." (PMID 29707121, 2018). "It is known that in addition of increasing proliferation of cancer cells, FoxM1 plays a major role in increasing the capability of cancer cells to invade surrounding tissues and migrate to other regions thereby increasing the metastatic potential in various cancers." (PMID 29707121, 2018). "However, the links between FoxM1 and cancer metabolism has been yet fully investigated." (PMID 29765517, 2018). "Interestingly, FoxM1 has an integral role in cancer initiation and cancer drug response, indicating that FoxM1 might be a new and effective therapeutic target for the elimination of CSCs." (PMID 30416986, 2018). "Additionally, the effect of FoxM1 on the capacity of cancer stem cells to self-renew was examined." (PMID 30416986, 2018). "A high-throughput screening identified a thiazole antibiotics Syomycin A as a potent FoxM1 inhibitor and thiostrepton, a similar type of thiazole antibiotics, has been shown to inhibit FoxM1 transcriptional activity by direct binding to FoxM1 in several human cancer cells including HCC cells." (PMID 29765517, 2018). "Hence, a comprehensive review of FOXM1 regulation will thus contribute to the extensive effort and research into the gene as a therapeutic target for a number of FOXM1-dependent conditions, such as the cancers mentioned previously." (PMID 30208972, 2018). "Therefore, targeting FOXO3, FOXM1 and other upstream or downstream targets in the signalling pathways, could be a feasible strategy for cancer treatment and for overwhelming drug resistance." (PMID 29180117, 2018). "Thus, integration of bortezomib into the standard SCLC therapy may ultimately improve the outcome of patients and be of high value in a wide range of FOXM1-driven cancers." (PMID 29228593, 2017). "However, in later stages, FOXM1 activation will promote cancer cell migration and invasion." (PMID 28978107, 2017). "FOXM1 Apt was confirmed to prevent the binding of FOXM1 to its consensus binding sites in promoters and consequently suppress FOXM1 transcriptional activities, resulting in the downregulation of the expression of FOXM1 target genes and the inhibition of cancer cell proliferation." (PMID 28358012, 2017). "Inhibition of FOXM1 expression in human cancer cells could potentially suppress tumorigenesis." (PMID 28977880, 2017). "DFS may be useful in treating cancers that feature the elevated expression of FoxM1." (PMID 28378765, 2017). "Increasing reports showed that FOXM1 might facilitate the growth and metastasis of cancer cells." (PMID 28978107, 2017). "Moreover, bortezomib and other proteasome inhibitors, such as the clinically undocumented but experimentally used proteasome inhibitor siomycin A, were also shown to induce apoptosis of cancer cells by inhibiting the activity and overexpression of Mammalian Forkhead box M1 (FOXM1)." (PMID 29228593, 2017). "In the early stage, FOXM1 may be inactivated, which contributes to cancer cell proliferation." (PMID 28978107, 2017). "Therefore, the attenuation of the DNA binding ability of FOXM1 could suppress FOXM1 transcriptional activities and represent a potent strategy targeting FOXM1 in cancer cells." (PMID 28358012, 2017). "Moreover, we found that FOXM1 overexpression in tumor tissue was also significantly correlated with the 3-year OS (OR = 2.62, 95% CI = 1.62 to 4.26, P < 0.0001) and 5-year OS (OR = 3.12, 95% CI = 1.56 to 6.28, P = 0.001) of patients with cancer in early stage." (PMID 28427178, 2017). "Thus, FOXM1 is likely to be used as an effective target for cancer patients." (PMID 28978107, 2017). "However, FoxM1 is frequently overexpressed in a wide spectrum of human cancers." (PMID 28953239, 2017).
cancer (continued). "Furthermore, we and others have shown that FOXM1 is involved in contra-acting stresses induced by cytotoxic or genotoxic signals, such as oxidative stress or DNA damage, and enhances the drug resistance of cancer cells." (PMID 28358012, 2017). "Therefore, a better understanding of the mechanisms that regulates FOXM1 expression in response to genotoxic agents and how FOXM1 is deregulated in resistant cancer cells is of importance for designing new therapeutic approaches directed to this degradation pathway." (PMID 26148240, 2016). "Therefore, exploring how FOXM1 is regulated in cells might provide a significant impact on the design of anti-cancer therapeutics." (PMID 27542221, 2016). "Furthermore, the oncogenic effects of cyclin D1 is well established and inhibition of CyclinD1 inhibits not only tumor cell growth or proliferation also suppresses tumor growth in mice, indicating the significance of FOXM1/EF2K/CyclinD1 axis in TNBC cancer biology and progression." (PMID 26918606, 2016). "Furthermore we analyzed the effect of miR-149 overexpression in two HCC cell lines, HepG2 and MHCC97H, on the expression of PPM1F and other putative target genes (GIT1, SP1, FOXM1) previously reported by other groups to promote migration and invasion in other cancer cell lines." (PMID 26498692, 2015). "It has also been proposed that FOXM1 could be the “Achilles heel” of cancer." (PMID 26258070, 2015). "Moreover, in vivo and in vitro studies have also showed that FoxM1 depletion results in a significant reduction of cancer cell proliferation and tumor formation, suggesting that the consecutive expression of FoxM1 may act as a crucial factor for tumor growth." (PMID 25869208, 2015). "Thus, FOXM1 is essential for cancer cell growth and survival." (PMID 26640950, 2015). "In addition, our studies identify FoxM1 as a potential therapeutic target in several cancer types." (PMID 25426548, 2014). "Therefore, combination of chemotherapy or IR with FoxM1 inhibition might improve the efficacy of those cancer treatments." (PMID 23467617, 2013). "In fact, it was earlier proposed that FoxM1 may be the ‘Achilles’ heel’ of cancer." (PMID 23857410, 2013). "Hence, FOXM1 not only promotes tumorigenesis by endowing proliferative capacity and leading to uncontrolled cell division at the early period of cancer development but also enhances other tumorigenic behaviors in other stages of cancer development." (PMID 21858223, 2011). "Moreover, it has recently been reported that FOXO3a can be modulated by oncogenes such as MUC1 causing increased DNA repair and enhanced cell survival in response to oxidative stress and recently FOXM1 was shown in a cancer cell line to stimulate DNA repair genes following genotoxic stress." (PMID 20187950, 2010). "In addition, we showed that overexpression of FoxM1 could protect cancer cells against thiopeptide-mediated apoptosis." (PMID 19440351, 2009). "A BRD4 degrader (ZBC260) achieved potent BRD4 depletion at low nanomolar doses, suppressed FOXM1/MYC and HR gene expression, enhanced PARP1 trapping, and produced strong synergy with olaparib, including in patient-derived cancer cells." (PMID 41820523, 2026). "mRNA expression analysis revealed that FOXM1 and MCM3 were upregulated, whereas SH3BP5 and PAPSS2 were downregulated in cancer tissues compared with normal tissues." (PMID 41750695, 2026).